SMPD3 (sphingomyelin phosphodiesterase 3)
Description:
Catalyzes the hydrolysis of sphingomyelin to form ceramide and phosphocholine. Ceramide mediates numerous cellular functions, such as apoptosis and growth arrest, and is capable of regulating these 2 cellular events independently. Also hydrolyzes sphingosylphosphocholine. Regulates the cell cycle by acting as a growth suppressor in confluent cells. Probably acts as a regulator of postnatal development and participates in bone and dentin mineralization. Binds to anionic phospholipids (APLs) such as phosphatidylserine (PS) and phosphatidic acid (PA) that modulate enzymatic activity and subcellular location. May be involved in IL-1-beta-induced JNK activation in hepatocytes (By similarity). May act as a mediator in transcriptional regulation of NOS2/iNOS via the NF-kappa-B activation under inflammatory conditions (By similarity).
Synonyms: nSMase2
Tractability: Small molecule: a high-quality ligand is known. Antibody: UniProt places it where antibodies can reach, with high confidence; its Gene Ontology location is reachable by antibodies, with high confidence. PROTAC: ubiquitination databases record sites on it; its protein half-life has been measured; a small molecule that binds it is known.
Target class: Enzyme; Hydrolase
Gene: Protein-coding gene on chromosome 16 (68,358,327 to 68,448,508, reverse strand). Ensembl gene ENSG00000103056.
Subcellular location: Golgi apparatus membrane; Cell membrane
Subcellular location (Human Protein Atlas): Endoplasmic reticulum
Pathways (Reactome):
Metabolism: Glycosphingolipid catabolism
Signal Transduction: TNFR1-mediated ceramide production
Gene Ontology:
Molecular function: phosphoric diester hydrolase activity; protein binding; sphingomyelin phosphodiesterase activity; phosphatidic acid binding; phosphatidylserine binding; catalytic activity; identical protein binding; neutral sphingomyelin phosphodiesterase activity
Biological process: sphingomyelin catabolic process; positive regulation of exosomal secretion; sphingomyelin metabolic process; sphingolipid metabolic process
Cellular component: endoplasmic reticulum; Golgi membrane; plasma membrane; cytoplasm; extracellular region; Golgi apparatus; Golgi cis cisterna
Genetic constraint (gnomAD): Loss-of-function variants: 21 observed, 50.39 expected, observed/expected ratio (o/e) 0.42, 90% interval 0.29 to 0.6. The upper end of that interval is the gene's LOEUF score, 0.6, which puts it in group 2 of 6, group 1 being the genes least tolerant of losing a copy. Missense variants: 842 observed, 881.96 expected, observed/expected ratio (o/e) 0.95, 90% interval 0.9 to 1.01. Synonymous variants: 457 observed, 396.91 expected, observed/expected ratio (o/e) 1.15, 90% interval 1.07 to 1.24.
Homologues: Orthologues: chimpanzee SMPD3 (99% identical), macaque SMPD3 (99% identical), mouse Smpd3 (91% identical), rat Smpd3 (91% identical), guinea pig SMPD3 (91% identical), rabbit SMPD3 (90% identical), pig SMPD3 (90% identical), dog SMPD3 (89% identical), tropical clawed frog smpd3 (68% identical), zebrafish smpd3 (58% identical).
Diseases named in the same sentence as SMPD3 in open-access papers:
SMPD3 is named in the same sentence as 109 diseases in open-access papers, as found by Europe PMC text mining. Sharing a sentence is not in itself a finding about the gene and the disease. The quoted sentences say what the papers report.
breast carcinoma (30 papers, 2013 to 2025). "SMPD3 as a potential tumor suppressor gene has gained widely studies, and it is linked to numerous malignancies like leukemia, breast cancer, and liver cancer." (PMID 30065754, 2018). "Comparing our results with existing literature, previous studies in other cancer types have shown SMPD3 to have tumor-suppressive properties, such as in colorectal and breast cancers." (PMID 40226357, 2025). "could show that inhibition of SMPD2 and SMPD3 gene expression as well as inhibition of nSMase activity through GW4869 enhanced lEV release from a breast cancer cell line." (PMID 34951654, 2021). "Also, abnormal promoter methylation of SMPD3 has been reported in breast cancer, colorectal cancer, clear cell renal cell carcinoma, and hepatocellular carcinoma cells." (PMID 30065754, 2018). "Interestingly, Smpd3 has been identified as a RA induced gene in MCF7 breast carcinoma cells and mouse embryonic stem cells treated for 12–24 h with retinoic acid and nSMase2 activity is regulated a number of factors eg. pro-inflammatory cytokines and phosphorylation." (PMID 36894641, 2023). "In addition, the downregulation of neutral SMase 2 (NSMase2, also known as SMPD3) contributes to melanoma immune escape to enhance tumor progression, while the overexpression of wild-type nSMase2 enhances the efficacy of anti-PD-1 antibody therapy in both melanoma and breast cancer mouse models." (PMID 35565311, 2022).
hepatocellular carcinoma (10 papers, 2018 to 2025). A malignant tumor that arises from hepatocytes. "n-SMase2, encoded by SMPD3, catalyzes SM catabolism to produce the anti-tumor metabolite Cer, and is associated with early postoperative recurrence of hepatocellular carcinoma." (PMID 37513239, 2023). "In colorectal cancer cells (CRCs) and hepatocellular carcinoma cells, sphingomyelin phosphodiesterase 3 (SMPD3) is also involved in miRNA encapsulation, and SMPD3 inhibition decreases exomiR levels in CRC cells while increasing intracellular miRNA levels." (PMID 38298209, 2024). "In CRC and hepatocellular carcinoma cell lines, it has been shown that sphingomyelin phosphodiesterase 3 (SMPD3), which also generates ceramide from sphingomyelin, is also involved in miRNA encapsulation." (PMID 31737071, 2019). "Indeed, hypermethylation of SMPD3 has been reported in various cancer types, including clear cell renal cell carcinoma and hepatocellular carcinoma." (PMID 32082486, 2020). "Similarly, an integrative genomic analysis revealed that SMPD3 is a tumor suppressor gene that could influence the aggressiveness of the hepatocellular carcinoma (HCC)." (PMID 38095640, 2023).
prostate carcinoma (10 papers, 2015 to 2024). A carcinoma that arises from epithelial cells of the prostate gland. "Of these 8 secretion-related genes, 5 genes (FKBP1B, SCIN, SMPD3, STEAP2, and TRIM36) has been associated with prostate cancer and hyperplasia." (PMID 26113971, 2015).
Alzheimer disease (9 papers, 2015 to 2025). A progressive, neurodegenerative disease characterized by loss of function and death of nerve cells in several areas of the brain leading to loss of cognitive function such as memory and language. "Previous studies have shown that Smpd3 deletion in mouse models causes juvenile dwarfism, delayed puberty, skeletal growth inhibition due to disruption of the Golgi secretory pathway of chondrocytes and progressive cognitive impairment similar to Alzheimer's disease." (PMID 39470011, 2024).
atherosclerosis (9 papers, 2020 to 2025). A disease characterized by the build-up of fatty material and calcium deposition in the arterial wall resulting in partial or complete occlusion of the arterial lumen. "As an important factor involved in macrophage polarization and inflammatory response, SMPD3 plays important roles in cardiovascular diseases, such as atherosclerosis, which is an important risk factor for AAA." (PMID 38913045, 2024). "Smpd3/nSMase2 is key to an alternative ceramide generation pathway (via sphingomyelin hydrolysis) that has recently been linked to atherosclerosis via regulation of serum ceramide levels." (PMID 36894641, 2023). "It has also been shown that nSMase2/Smpd3 deficiency or inhibition strongly suppresses M1 macrophage infiltration and differentiation, and inhibits inflammation, in a mouse model of atherosclerosis via Nrf2 (NF-E2-related factor 2)/HO-1 pathway activation." (PMID 33208172, 2020). "Despite these beneficial metabolic effects, a clear worsening of atherosclerosis was established in this atherosclerosis‐prone mouse model, which appears to involve an alternative ceramide generation pathway (via sphingomyelin hydrolysis) regulated by Smpd3/nSMase2." (PMID 36894641, 2023). "Our data suggest the putative mechanism of increased atherosclerosis with FEN treatment is via the upregulation of the gene encoding type 2-neutral sphingomyelinase (nSMase 2, gene Smpd3), an alternative ceramide generation pathway (via sphingomyelin hydrolysis)." (PMID 36894641, 2023). "Neutral sphingomyelinase (Smpd3), encoding for nSMase2, was recently identified as an FXR target gene mediating the effects on intestinal ceramide (mainly C16:0) production and secretion, also in the pathophysiology of atherosclerosis." (PMID 35789435, 2022). "It is also reported that there is excessive accumulation of cholesterol in the arterial wall with dysregulation of ceramide metabolism in patients with atherosclerosis, and sphingomyelin phosphodiesterase 3 (SMPD3) serves as a key enzyme that promotes the sphingomyelin to hydrolyze into ceramide." (PMID 36278234, 2022). "Interestingly, circulating ceramides derived from the intestine promote the development of atherosclerosis, and decreasing plasma ceramides through suppression of the intestinal FXR/Smpd3 axis reduced lesion areas in the aortas of ApoE-deficient mice." (PMID 35789435, 2022).
melanoma (9 papers, 2019 to 2023). A malignant, usually aggressive tumor composed of atypical, neoplastic melanocytes. "The SMPD3 catalyses sphingomyelin to ceramide, and the degradation of ceramide into sphingosine is associated with melanoma progression." (PMID 34199079, 2021). "TCGA database of SKCM also showed a strong positive correlation between expressions of SMPD3 and IFNB1 in melanoma tissues, suggesting that TEVs increased IFN-β expression in human melanoma tissues." (PMID 34751648, 2021).
colorectal cancer (6 papers, 2015 to 2024). A primary or metastatic malignant neoplasm that affects the colon or rectum. "In addition, we examined the evolutionary conservation of SMPD3 in mammals and determined the effects of an SMPD3 inhibitor on the release of small/microRNAs from HuH-7 and SW480 human colorectal cancer cells." (PMID 25394686, 2015).
Hepatic steatosis (6 papers, 2021 to 2025). Steatosis is a term used to denote lipid accumulation within hepatocytes. "While our findings and previous literature suggest potential mechanisms by which Smpd3, Dtl, Cdc6, Top2a, and Mki67 contribute to liver steatosis, further study is needed to clarify their precise roles." (PMID 40687776, 2025). "The present study identified five genes (Smpd3, Dtl, Cdc6, Top2a, and Mki67) as potential mediators in the development of WD-induced liver steatosis." (PMID 40687776, 2025). "In conclusion, transcriptomic analysis of the livers from HFD-fed mice with liver steatosis identified a significant upregulation in Smpd3 (nSMase2), a key finding that led to the development of a HepG2 human cell model of induced steatosis by using glucolipotoxic stress conditions." (PMID 38474427, 2024). "Furthermore, this study basically focuses on the role of nSMase2/Smpd3, thus overlooking other critical pathways and factors that could be involved in hepatic steatosis." (PMID 38474427, 2024).
Anxiety (5 papers, 2018 to 2022). Intense feelings of nervousness, tension, or panic often arise in response to interpersonal stresses. "The results exhibited a loss of the Smpd3 gene modulates anxiety behavior and stress responses, as well as the recovery of brain-derived neurotrophic factor (BDNF) expression, through exosomal miRNA in the hippocampus." (PMID 35163475, 2022). "Our results suggest that SMPD3 is associated with behavioural outcomes including alcohol consumption, as well as with anxiety and depressive symptoms." (PMID 34584229, 2021). "Furthermore, loss of the nSMase2/Smpd3 gene in mdx mice suppressed abnormal emotional behavior, such as the stress-induced anxiety response, as well as the recovery of hippocampal Bdnf expression." (PMID 33208172, 2020). "Combined, these findings suggest that ablation of the nSMase2/Smpd3 gene in mdx mice modulates their anxiety behavior and stress response." (PMID 33208172, 2020). "Thus, to investigate anxiety, emotionality, and the adaptive stress response to a novel environment in mdx:Smpd3 DKO mice, the hole-board test was performed." (PMID 35163475, 2022). "In addition, the mdx:Smpd3−/− mice performed significantly fewer head-dips (a marker of anxiety behavior in the hole-board test) than the mdx mice." (PMID 33208172, 2020). "A genetic association analysis in 456,693 volunteers found an association of numerous haplotypes of the SMPD3 gene, coding for the enzyme neutral sphingomyelinase-2 (NSM), with alcohol consumption, depression, and anxiety." (PMID 35959215, 2022). "We therefore propose SMPD3 and its coded protein NSM as a joint base for the frequently comorbid symptom trias of alcohol addiction—depression/anxiety—osteoporosis." (PMID 34584229, 2021).
dwarfism (5 papers, 2014 to 2024). "The inactivation of SMPD3 causes skeletal malformations, whereas SMPD3 deficiency can result in juvenile dwarfism in neutral sphingomyelinase (SMPD3) mice, suggesting that SMPD3 is a polygenetic determinant of body height." (PMID 37761812, 2023). "This study is focused on the mechanism underlying SMPD3 deficiency, which causes systemic and cell-specific growth inhibition, a novel form of juvenile dwarfism." (PMID 27882938, 2016). "Systemic loss of neutral sphingomyelinase (SMPD3) in mice leads to a novel form of systemic, juvenile hypoplasia (dwarfism)." (PMID 27882938, 2016). "SMPD3 is the primary regulator of ceramide biosynthesis, and plays a pivotal role in the control of late embryonic and postnatal development such that defects in the gene lead to dwarfism and pituitary hormone deficiency." (PMID 24964093, 2014).
steatosis (5 papers, 2023 to 2025). Increased lipid within the cytoplasm of cells. "A marked increase in Smpd3 expression in the liver, which has previously been linked to steatosis, was also detected in infected mice." (PMID 40618034, 2025). "Notably, the gene encoding neutral sphingomyelinase, SMPD3, was predominantly upregulated in the liver tissues of the mice displaying a phenotype of steatosis." (PMID 38474427, 2024). "By integrating data from the two RNA sequencing analyses, we identified five molecules related to cell division: Smpd3, Dtl, Cdc6, Mki67, and Top2a, as key mediators in suppressing WD-induced steatosis in hepAGT −/− mice." (PMID 40687776, 2025). "Increased abundances of Smpd3, Dtl, Cdc6, Mki67, and Top2a were detected after 14 and 42 days of feeding WD, which was consistent with the initiation and advanced phases of steatosis in hepAGT +/+ mice." (PMID 40687776, 2025). "In our cells model, we also found a significant upregulation of Smpd3 expression and nSMase2 activity under steatosis-promoting conditions, similar to the increased nSMase2 activity in the liver tissues of HFD-fed mice." (PMID 38474427, 2024).
depression (4 papers, 2021 to 2023). "In addition to the inflammatory regulators, another top gene in topic 10, sphingomyelin phosphodiesterase 3 (SMPD3), has also been associated with depression and AD treatment response." (PMID 37186582, 2023).
glioma (4 papers, 2013 to 2022). A benign or malignant brain and spinal cord tumor that arises from glial cells (astrocytes, oligodendrocytes, ependymal cells). "Interestingly, amongst all of the highly expressed genes in this pathway, SMPD3 overexpression was associated with improved survival in both IDHmut and IDHWT; however, it was more significant in IDH1mut lower grade gliomas (p value of 1.2 × 10−8 for IDHmut compared with 1.7 × 10−3 for IDHWT)." (PMID 33050528, 2020). "We also compared the mRNA levels for SMPD3, ASAH2 and other sphingolipid genes available through the TCGA database between IDHmut (n = 218) and IDHWT (n = 68) from lower grade glioma and higher-grade glioblastomas." (PMID 33050528, 2020). "Patients’ samples with IDHmut consistently displayed significantly higher mRNA levels of SMPD3 and ASAH2 along with related genes in both lower grade glioma as well as high grade gliomas." (PMID 33050528, 2020). "Overall, Western blot analysis confirmed upregulation of key sphingolipid enzymes such as SMPD3 and ASAH2, in IDH1mut glioma cells specifically, which suggested that the pathway is upregulated towards the elevating the availability of sphingosine and ceramide." (PMID 33050528, 2020). "It comes as no surprise that higher SMPD3 expression in glioma patients dramatically improves patient survival." (PMID 36012521, 2022).
osteogenesis imperfecta (4 papers, 2010 to 2024). Osteogenesis imperfecta (OI) comprises a heterogeneous group of genetic disorders characterized by increased bone fragility, low bone mass, and susceptibility to bone fractures with variable severity. "The independently derived fragilitus ossium Smpd3 allele recovered from a forward genetic screen has osteogenesis imperfecta (‘brittle bone’ disease), shortened and bent long bones, tooth development issues and partially penetrant postnatal lethality." (PMID 39470011, 2024). "Regarding the strategy for nSMase2 blockade, the spontaneously derived mouse Smpd3 mutation characterized as fragilitas ossium (fro) confers severe developmental abnormalities in mice, including osteogenesis imperfecta and high perinatal mortality." (PMID 33507882, 2021). "Notably, deletion of the gene Smpd3, which encodes nSMase2, a membrane-bound enzyme that hydrolyses SM to phosphocholine and ceramide, results in mice displaying a severe osteogenesis imperfecta phenotype." (PMID 38474268, 2024).